SMAD2 (SMAD family member 2)
Diseases named in the same sentence as SMAD2 in open-access papers (continued):
Sharing a sentence is not in itself a finding about the gene and the disease.
gastric cancer (94 papers, 2010 to 2026). A primary or metastatic malignant neoplasm involving the stomach. "Activation of the TGFβ–Smad2 pathway is also involved in the differentiation of umbilical cord-derived MSCs to carcinoma-associated fibroblasts induced by gastric cancer exosomes." (PMID 36593485, 2023). "SMAD2 expression levels are low in EBV-associated gastric cancer, particularly in the presence of EBV-encoded latent membrane protein 2A (LMP2A)." (PMID 37685308, 2023). "In the HER2-positive gastric cancers, p-Smad2 and c-Met expression was associated with a poorer outcome." (PMID 35650563, 2022). "Activation of the TGFβ-SMAD2/3 pathway in Kupffer cells contributes to gastric cancer metastasis to the liver by causing Kupffer cells to promote activation of the CSC properties of incoming gastric cancer cells." (PMID 36497411, 2022). "In fact, meta-analysis of published microarray datasets revealed that increased TMEPAI and Smad3 expression and decreased Smad2 expression in lung and gastric cancers was significantly associated with poorer patient prognosis." (PMID 31798766, 2019). "The expression of p-Smad2 is associated with malignant phenotype and poor prognosis in patients with advanced gastric carcinoma." (PMID 21110833, 2010). "Since the activated Smad2 was associated with the malignant phenotype of gastric cancer, it is possible that inhibition of p-Smad2 signaling in gastric carcinoma may yield beneficial effects through inhibition of invasion and metastasis of cancer." (PMID 21110833, 2010). "The activated Smad2 level might be associated with the different clinical phenotype of malignancy between the diffuse-type and intestinal-type in gastric carcinoma." (PMID 21110833, 2010). "The heterogeneity may provide the opportunity for clonal evolution, and the intra-tumoral heterogeneous clonal evolution of signaling such as that by p-Smad2 and c-Met might be associated with the acquisition of lymph-node metastatic ability in gastric cancer cells." (PMID 35650563, 2022). "The silencing of USP32 has been shown to suppress gastric cancer tumorigenesis through the modulation of SMAD2 expression." (PMID 41356798, 2026). "Growing evidence suggests that itraconazole not only suppresses cancer via the TGF-β/SMAD2/3 signaling pathway, but also exerts antitumor effects on various cancer cells (endometrial cancer and gastric cancer)via Hh signaling pathway." (PMID 39917616, 2025). "In fact, the overexpression of SMAD2 has been shown to negatively correlate with the expression of E-cadherin, contributing to poor prognosis in gastric cancer patients." (PMID 40134588, 2025). "TRIM22 directly interacts with Smad2 to suppress gastric cancer cell proliferation, and Smad2 overexpression counteracts TRIM22-mediated inhibition of cell proliferation and migration." (PMID 40936722, 2025). "In vitro, its silencing inhibited cancer cell migration and invasion and reduced phospho-Smad2 and phospho-Smad4 levels, while its ectopic expression promoted gastric cancer progression and counteracted TGF-β inhibitors." (PMID 39768197, 2024). "For instance, cytotoxin-associated gene A (CagA), a major virulence factor in Helicobacter pylori, promotes the progression of gastric cancer through the miR-155-5p/SMAD2/SP1 axis." (PMID 38689341, 2024). "USP32 overexpression in gastric cancer (GC) enhances SMAD2 deubiquitination, correlating with advanced tumor stages, increased cisplatin resistance, and poorer survival." (PMID 38702734, 2024). "For instance, ITD‐1, a drug that suppresses TGFβ2, prevents Smad2/3 phosphorylation, thereby inhibiting glioma cell and gastric cancer cell invasion." (PMID 38531630, 2024). "Gastric cancer cells activate fibroblasts via the TGF-β1/Smad2/3 signaling pathway, enhancing HAPLN1 expression to promote tumor migration and invasion." (PMID 39850884, 2024). "SMAD2 is a key element of transforming growth factor signaling pathway in the occurrence and development of gastric cancer." (PMID 37679322, 2023).
gastric cancer (continued). "Downregulation of USP32 can significantly inhibit the expression of SMAD2, thereby inhibiting the proliferation, migration, and chemoresistance to cisplatin of gastric cancer cells." (PMID 37143582, 2023). "In gastric cancer, ubiquitin-related enzymes such as TRIM22 and USP32 promote the proliferation and invasion of gastric cancer cells by affecting the stability of the SMAD2 protein, which is highly expressed in gastric cancer." (PMID 37685308, 2023). "MFAP2 was reported to promote EMT by activating TGF‐β/SMAD2/3 signalling pathway in gastric cancer cells." (PMID 37635348, 2023). "In the HER2-positive gastric cancer cases, the co-expression of p-Smad2/c-Met was significantly correlated with the pathological stage (p = 0.042) and tended to be correlated with the T stage (p = 0.104) and N stage (p = 0.098)." (PMID 35650563, 2022). "In PTCH1mut cells, dysregulated Hh signalling is associated with the upregulation of SMAD2, 3, and 4 mRNA, as was also shown for SMAD3 in gastric cancers." (PMID 35159339, 2022). "ASPN is thought to activate the SMAD2 pathway to induce EMT, as higher levels of phosphorylated SMAD2 have been observed in gastric cancer tissue compared with adjacent normal tissue." (PMID 36358747, 2022). "In the present cases of HER2-positive GC, the prognosis of the patients with both p-Smad2-positive and c-Met-positive gastric cancer was significantly poorer than the prognosis of other cases." (PMID 35650563, 2022). "Mechanically, gastric cancer cells activate fibroblasts to up-regulate HAPLN1 expression via activation of TGF-β1/Smad2/3 signaling, which in turn promotes tumour migration and invasion." (PMID 34724589, 2022). "The overall survival (OS) of the HER2-positive gastric cancer patients with p-Smad2 and c-Met expression (n = 13) was significantly poorer than that of the patients with p-Smad2-negative and/or c-Met-negative expression (n = 30) (p = 0.030)." (PMID 35650563, 2022). "On the other hand, MIR4435-2HG knockdown leads to the inhibition of transforming growth factor beta (TGF-β) and phosphorylated SMAD2 (p-SMAD2) in gastric cancer cell lines." (PMID 35715800, 2022). "In the cases of HER2-negative gastric cancer, there was a significant correlation between the co-expression of p-Smad2 and c-Met and the microscopic type (p = 0.006)." (PMID 35650563, 2022). "The results of the cluster analysis also indicated that in HER2-positive gastric cancer, the co-expression of p-Smad2 and c-Met was related to lymph node metastasis." (PMID 35650563, 2022). "We further reveal that gastric cancer cells can activate fibroblasts to up-regulate HAPLN1 expression via the TGF-β1/Smad2/3 signaling activation, and that CAFs-derived HAPLN1 promotes tumour invasion through ECM remodeling." (PMID 34724589, 2022). "Gastric cancer cells can activate fibroblasts to up-regulate HAPLN1 expression via activation of TGF-β1/Smad2/3 signaling." (PMID 34724589, 2022). "Treatment with gastric cancer cell CM also increased Smad2/3 expression in Hs738 cells, while neutralization with anti-TGF-β1 inhibited these effects accordingly." (PMID 34724589, 2022). "The ability of MFAP2 in activating TGF-β/SMAD2/3 pathway in gastric carcinoma has also been reported, and this activation accelerates the transformation of gastric carcinoma from an epithelial cell phenotype to a mesenchymal phenotype." (PMID 35211173, 2022). "SMAD1, SMAD2, and SMAD4 are associated with favorable OS in the first and third stage of gastric cancer." (PMID 34138687, 2021). "Analysis showed that high expression levels of SMAD1, SMAD2, and SMAD4 are associated with a better survival rate of gastric cancer patients, whereas SMAD3, SMAD5, SMAD6, SMAD7 and SMAD9 are associated with poor prognosis." (PMID 34138687, 2021). "This study shows that high expression level of SMAD1, SMAD2, and SMAD4 is associated with favorable OS of gastric cancer patients." (PMID 34138687, 2021).
gastric cancer (continued). "For example, activation of the TGF-β/Smad2 signaling pathway mediated by HMMR contributes to the chemoresistance of gastric cancer." (PMID 34595101, 2021). "The results showed that the expression of p-Smad2 and p-Smad3 in metastatic gastric cancer cells was obviously higher than those in primary gastric cancer cells." (PMID 32139657, 2020). "The expressions of p-Smad2 and p-Smad3 in peritoneal mesothelial cells were significantly upregulated in the presence of metastatic gastric cancer cell supernatants." (PMID 32139657, 2020). "HMMR can induce epithelial-mesenchymal transition (EMT) and exert oncogenic effects through activating the TGF-β/Smad2 signaling pathway in gastric cancer." (PMID 33061798, 2020). "We demonstrated that MIR17HG-derived miR-18a and miR-19a coordinately mediate gastric cancer cell metastasis by directly inhibiting SMAD2 expression and upregulating Wnt/β-catenin signalling." (PMID 31186404, 2019). "It is known that the overexpression of SMAD2, a regulator of cell proliferation, apoptosis and differentiation, is correlated with poor survival of gastric carcinoma, gliomas and non-small cell lung cancer." (PMID 27006471, 2016). "We then demonstrated that gastric cancer cell-derived exosomes stimulated the phosphorylation of Smad-2 in hucMSCs." (PMID 23285052, 2012). "Though in majority of the cancers underexpression of tumor suppressor SMAD2 has been reported, in a few cancers such as Pancreatic cancer and Gastric cancer, an overexpression of this protein has been observed." (PMID 24688641, 2012). "Smad2 phosphorylation was increased by TGF-β1 (10 ng ml−1) in scirrhous gastric cancer cell lines, OCUM-2MLN and OCUM-12." (PMID 20145621, 2010). "Because of the dual role of TGFβ in oncogenesis, depending on the type and stage of the tumour, we focused our study on p-Smad2 expression on the advanced stage of gastric cancer." (PMID 21110833, 2010). "In this study, a TβR-I inhibitor, Ki26894, displayed inhibitory activity against phosphorylation of Smad2 in scirrhous gastric cancer, suggesting that the small-molecule compound Ki26894 is a potent TβR kinase inhibitor." (PMID 20145621, 2010). "In this series of advanced gastric cancer, survival of phospho-Smad2 high level expression patients was significantly poorer than that of phospho-Smad2 low level expression patients (p = 0.035)." (PMID 21110833, 2010). "In this study, therefore, we investigated the p-Smad2 expression of gastric carcinoma to clarify the role of p-Smad2 in advanced gastric adenocarcinomas." (PMID 21110833, 2010). "Compared with the blank group, the expression of p-Smad2 protein in gastric cancer cells (Hgc27 and MKN45) in the M2c co culture group showed the same trend, while there was a significant difference in Smad2 protein expression between the two gastric cancer cell lines in the M2c co culture group." (PMID 39991579, 2025). "In addition, MIR17HG can enhance the expression of mir‐18a and mir‐19a, suppress the expression of Smad2, and upregulate Wnt/β‐Catenin signaling, thereby facilitating the metastasis of gastric cancer cells." (PMID 38321787, 2024). "In addition, RHAMM has been reported to confer chemoresistance by inducing EMT via TGFβ/Smad2 in gastric cancer." (PMID 39518040, 2024). "USP32 enhances gastric cancer growth and drug resistance by increasing SMAD2 levels." (PMID 39605891, 2024). "Meanwhile, rescue experiments showed that overexpression of SMAD2 could reverse the effects of silenced USP32 on gastric cancer cell growth, metastasis and cisplatin resistance." (PMID 37679322, 2023). "Furthermore, MFAP2 was found to promote epithelial–mesenchymal transition of gastric cancer cells by activating TGF‐β/SMAD2/3 signalling pathway." (PMID 37635348, 2023). "The use of a c-Met inhibitor or a p-Smad2 inhibitor in combination with a HER2 inhibitor might be promising against lymph node metastasis in patients with HER2-positive gastric cancer." (PMID 35650563, 2022).
gastric cancer (continued). "Furthermore, MFAP2 is found to be a possible player in TGF-β/SMAD2/3 signaling pathway activation to advance proliferation, migration, invasion, and epithelial-mesenchymal transition of gastric cancer cells." (PMID 35211173, 2022). "Furthermore, low levels of SMAD2 activation were positively correlated with reduced overall survival in ductal carcinoma of the breast and increased cancer invasion in gastric cancer." (PMID 35681731, 2022). "Besides, a recent study showed that ADAM17 knockdown inhibited the expression of TGF-β in gastric carcinoma cells, with the downstream Smad2 and Smad3 also being attenuated." (PMID 36313337, 2022). "Because TRIM22 could inhibit Smad2 phosphorylation, we speculated that TRIM22 might regulate the proliferation and migration of gastric cancer cells through Smad2." (PMID 34489426, 2021). "In conclusion, our results showed that TRIM22 expression was abnormally downregulated in gastric cancer and that TRIM22 could inhibit the proliferation and migration of gastric cancer cells by affecting Smad2 protein phosphorylation." (PMID 34489426, 2021). "Our study indicates that TRIM22 has an important role in the development of gastric cancer and may inhibit the proliferation of gastric cancer cells through Smad2." (PMID 34489426, 2021). "In addition, several investigations have indicated the oncogenic roles of SMAD2 in pancreatic cancer, gastric cancer, and prostate cancer 28-30." (PMID 32226309, 2020). "Kendall-tau correlation analysis revealed a potential correlation between reduction of P-Smad2C staining and the transition from normal to cancer cells in gastric cancer (p = 0.05), suggesting that activation of Smad2 signaling is a critical suppressor of tumor formation and progression." (PMID 22539990, 2012). "Besides measuring P-Smad2 in gastric cancer, we used real-time PCR to detect mRNA expression of Smad2 and Smad3 in gastric cancer and surrounding non-tumor tissues from 16 patients." (PMID 22539990, 2012). "Relationships between p-Smad2 and clinicopathological features in 135 gastric cancer cases." (PMID 21110833, 2010). "Phospho-Smad2 was expressed in the nucleus of scirrhous gastric cancer cells." (PMID 20145621, 2010). "Ki26894 decreased Smad2 phosphorylation induced by TGF-β1 in scirrhous gastric cancer cells." (PMID 20145621, 2010). "The high expression level of p-Smad2 was found in 63 (47%) of 135 gastric carcinomas." (PMID 21110833, 2010). "The p-Smad2 expression level was high in 63 (47%) of 135 gastric carcinomas." (PMID 21110833, 2010). "It has been found that USP32 is abundantly expressed in gastric cancer and that it regulates chemoresistance in GC and SMAD2 cells." (PMID 39030175, 2024). "A study in gastric cancer found that silencing of LINC00665 can downregulate the expression levels of TGF-β and its downstream factors Smad-2 and α-SMA, indicating that LINC00665 may promote the progression of EMT in gastric cancer through the TGF-β/Smad-2 signaling pathway." (PMID 35563845, 2022). "Examples of such escape include the mutation of SMAD4 in pancreatic ductal adenocarcinoma (PDAC) and gastric cancer (GC), the TβR I mutation in colon cancer, and even mutations in genes that encode TGF-β ligands (BMP5), receptors (TβR II, AVCR2A, BMPR2), and SMADs (SMAD2 and SMAD4)." (PMID 35461253, 2022). "Allred score system for p-Smad2 expression might be suitable for accurately assessing p-Smad2-expressing tumor cells, and might be adequate for predicting the outcome of patients with gastric cancer." (PMID 21110833, 2010). "Understanding the significance of Smad2 might be useful in gastric cancer." (PMID 21110833, 2010). "Exosomes containing NNMT, which were derived from gastric cancer cells, have the capacity to facilitate peritoneal metastasis through the activation of the TGF-β/Smad2 signaling pathway." (PMID 40708696, 2025).
gastric cancer (continued). "In scirrhous-type gastric cancer, CAFs were shown to upregulate the gastric CSC markers, CSC population, and their expression of TGF-βR1, TGF-βR2, and SMAD2." (PMID 38562556, 2024). "In gastric cancer cells, TRIM22 inhibits cancer cell proliferation and migration by reducing the phosphorylation of SMAD2." (PMID 38199981, 2024). "The present study revealedthat an exceptionally low concentrationof DEHP enhanced gastric cancer cell migration and promoted EMT bymodulating the PI3K/AKT/mTOR and Smad2 signaling pathways in DEHP-treatedMKN45 cells." (PMID 38574184, 2024). "The high expression of SMAD1, SMAD2, and SMAD4 in gastric cancer tissues is significantly correlated with the prognosis of patients." (PMID 36969909, 2023). "In human gastric cancer cell lines, MKN45 and KATOIII, TGF-β1 induced VEGF-C expression leading to lymphangiogenesis by activating Smad2/3 and Smad pathway." (PMID 36614038, 2022). "The band proteins intensities displayed that the proteins of p-Akt, p-Smad3, and β-catenin were remarkably downregulated but p-Smad2 was upregulated when added BBR (10, 20, and 40 μM for 24 h) in HepG2 and gastric cancer cells." (PMID 34712379, 2021). "The results showed that the high expression of three members of SMADs (SMAD1, SMAD2, SMAD4) was correlated with afavorable OS of gastric cancer patients." (PMID 34138687, 2021). "Collectively, these results demonstrate that the high expression level of three members of SMADs (SMAD1, SMAD2, and SMAD4) is significantly correlated with favorable OS of gastric cancer patients, which is opposite to SMAD3." (PMID 34138687, 2021). "TGF-β1 induced the activation of Smad2/3 and Smad pathway-modulated VEGF-C expression in gastric cancer cell line models." (PMID 31409309, 2019). "We verified the presence of TGF-β in gastric cancer cell derived exosomes and confirmed the TGF-β/TGF-β R1 interaction mediated the Smad2/3 activation and CAF differentiation in hucMSCs." (PMID 23285052, 2012). "We further confirmed that TGF-β receptor 1 kinase inhibitor attenuated Smad-2 phosphorylation and CAF marker expression in hucMSCs after exposure to gastric cancer cell-derived exosomes." (PMID 23285052, 2012). "Targeting this axis—through MAPK inhibition, SMAD2/3 blockade, or suppression of WNT secretion—may represent a therapeutic vulnerability in gastric cancer and other KRAS-high malignancies." (PMID 41398956, 2025). "Moreover, the anti-growth effect of TRIM22, which was observed in subcutaneous xenograft experiments, can be reversed by the upregulation of Smad2, indicating that TRIM22 suppressed gastric cancer progression by blocking the TGF-β/Smad pathway." (PMID 39768197, 2024). "In gastrointestinal tumors, miR-4429 has been reported to reduce METTL3 expression in gastric cancer, and another study reported that HOXA10 increases Smad2/3 expression in the nucleus and promotes METTL3 deposition to regulate the progression of EMT in gastric cancer." (PMID 38166703, 2024). "Furthermore, in gastric cancer, PCDHGA9 was shown to reduce SMAD2/3 nuclear translocation suppressing Snail expression, resulting in changes in cell–cell adhesion proteins, including E-cadherin." (PMID 37748077, 2023). "The expressions of p-Smad2 and c-Met might be predictive markers for prognosis and for targeting therapy in patients with HER2-positive gastric cancer." (PMID 35650563, 2022). "Similarly, the TGF-β1 signaling pathway was found to regulate the EMT of gastric cancer cells via miRNA-181b overexpression; the latest resulted in targeting the Tissue Inhibitor of Metalloproteinases 3 (TIMP3) gene through the Smad2/3/4-dependent pathway." (PMID 36613487, 2022). "p-Smad2 and c-Met signaling might play important roles in lymph node metastasis in HER2-positive gastric cancer." (PMID 35650563, 2022).